SIRT1 (sirtuin 1)
Diseases named in the same sentence as SIRT1 in open-access papers (continued):
Sharing a sentence is not in itself a finding about the gene and the disease.
cancer (continued). "Our result also indicated that the overall survival time of ESCC patients with positive SIRT1 expression was significantly lower than that of patients with negative SIRT1 expression after surgery (HR = 1.92), which meant that SIRT1 might be a cancer promoting factor." (PMID 35350833, 2022). "In cancer, SIRT1 may have dual functions as a tumor promoter or tumor suppressor." (PMID 35806366, 2022). "The studies also reported that SIRT1 could regulate cancer cell growth and apoptosis." (PMID 36552538, 2022). "SIRT1 can represent a candidate molecule to be targeted to protect ovarian follicles from alkylating agents and EX-527 could represent a potential fertoprotective agent for cancer patients." (PMID 35247119, 2022). "A lot of studies indicated that SIRT1 could serve as a candidate biomarker of human cancer." (PMID 35350833, 2022). "Consequently, one might have expected that the elevated expression levels of miR-34a observed in our study in both tumor types when compared with the control group would result in suppression of the SIRT1 expression, leading to apoptosis of cancer cells." (PMID 34771655, 2021). "However, SIRT1 has been found to be upregulated in several human cancers." (PMID 33384409, 2021). "SIRT1, a class III histone deacetylase, could increase the risk of cancer." (PMID 33345272, 2021). "In addition, our data, along with the evidence from MEFs, stem cells, and cancer cells, suggests that Sirt1 may play tissue- or cell type-dependent roles in autophagy." (PMID 33723227, 2021). "Furthermore, Res was shown able to induce cancer cell death by upregulating sirtuin 1 (Sirt1)." (PMID 34361819, 2021). "Importantly, SIRT1 overexpression has been discovered in many cancers, including CRC67." (PMID 33958586, 2021). "However, the role of SIRT1 in cancer progression and therapeutic responses remains controversial because SIRT1 has both tumor-promoting and tumor-suppressing functions, depending on whether oncogenes or tumor-suppressor genes are targeted." (PMID 34381712, 2021). "However, the impact of SIRT1 on EMT varies in various types of cancers." (PMID 34934771, 2021). "In our experiments, dunnione significantly increased SIRT1 levels, which were decreased in neutrophils cultured with cancer CM, suggesting that dunnione alleviates histone acetylation by increasing SIRT1 expression, which as a result reduces cancer-induced NETosis." (PMID 34769515, 2021). "Therefore, the state and activity of Sirt1 in cancer may play an essential role in cellular responses to epigenetic conditions and treatments." (PMID 33430318, 2021). "Therefore, activating SIRT1 to deacetylate FOXM1 may become an efficient strategy for treating cancers with overexpressed FOXM1." (PMID 34769241, 2021). "However, SIRT1 may reportedly act as a tumor suppressor in certain cellular conditions, suggesting its contradictory role in cancer development and progression." (PMID 34471223, 2021). "Therefore, we propose that LKB1-mediated Sirt1 activation may respond to energy restriction (such as glucose starvation) and play roles in aging and cancer, which needs further study." (PMID 34216621, 2021). "Moreover, SIRT1 promotes glucose transporting and inhibits apoptosis of cancer cells." (PMID 31900225, 2020). "The nicotine/nAChR signaling crosstalk with SIRT1/3/5-7 may contribute to cancer drug resistance." (PMID 31956359, 2020).
cancer (continued). "Indeed, we are lacking even a minimal understanding of how pharmacological manipulations targeting core metabolic checkpoints such as AMPK, mTOR, and SIRT1, might fine-tune the expression of immune checkpoint receptors in cancer cells." (PMID 31901900, 2020). "According to previous reports and our findings, we suspected that SIRT1−/− cells displayed the morphological phenotype of mitotic catastrophe, which is a mitotic cell death pattern distinct from apoptosis, necrosis, or senescence, and is considered as a desirable end point in cancer therapy." (PMID 31209362, 2020). "Like other molecules being responsible for epigenetic alterations, SIRT1 affects the cell-cycle via multiple pathways: besides the regulation of lipid and glucose metabolism, it is also involved in the pathogenesis of cancer by deacetylation of different histones." (PMID 32388637, 2020). "(iv) SIRT1 could both enhance the lifespan and diminish those hazards from claiming cancer." (PMID 32607257, 2020). "SIRT1 further co-localizes with GR in the nucleus upon dexamethasone treatment and regulates GR transcriptional activity by cooperating with PGC1α in a deacetylase independent manner as shown in three different human cancer (cervical, colon, hepatic) cell lines." (PMID 33330467, 2020). "Other molecular signaling pathways such as the Wnt signaling pathway, phosphoinositide 3-kinase-related protein kinase (PI3K), nuclear factor erythroid 2-related factor 2 (Nrf2), and sirtuin 1 (SIRT1) may also be involved in the resistance of cancer cells to CP therapy." (PMID 32503307, 2020). "Moreover, SIRT1 enhances progression and epithelial-mesenchymal transition in several cancer." (PMID 31900225, 2020). "Together, these results suggest that CHK2 mediates the function of SIRT1 in cell cycle progression, and may provide new insights into modulating cellular homeostasis and maintaining genomic integrity in the prevention of aging and cancer." (PMID 31209362, 2020). "However, emerging evidence suggests that SIRT1 can promote cancer drug resistance." (PMID 31956359, 2020). "Consistent with this notion, the subcellular localization of SIRT1 actually accounts for its differential actions: in particular, nuclear SIRT1 is endowed with protective anti-inflammatory action, while cytoplasm-localized SIRT1 was shown to enhance apoptosis in different cancer cell lines." (PMID 32120833, 2020). "While SIRT1 is shown to promote many cancer phenotypes, a positive regulator of many cancer hallmarks, and is overexpressed in human cancer specimens compared to normal tissue, some reports from transgenic mouse models have identified tumor suppressor properties of SIRT1." (PMID 33330467, 2020). "Therefore, SIRT1 mediated autophagy may be a potential target for inhibiting EMT during cancer progression." (PMID 30674969, 2019). "Thus, SIRT1’s role as a DNA repair promoter and guardian of genomic stability is clear, but its relationship with tumorigenesis induction is not fully understood and studies that elucidate these pathways will provide a breakthrough in cancer biology." (PMID 31261609, 2019). "Moreover, SIRT1-mediated deacetylation regulates YAP in cancer cells." (PMID 31689236, 2019). "Therefore, SIRT1 may be a therapeutic target for inhibiting cancer metastasis driven by Ang II, and PPD may be an alternative candidate for developing combined targeted therapies antagonistic to Ang II in NSCLC." (PMID 31133857, 2019).
cancer (continued). "Interestingly, SIRT1 seems to play a tumor suppressor role, since it is downregulated in several types of cancer, including prostate cancer, ovarian cancer, liver cancer and glioblastoma, with its over-expression in mice delaying the development of KRASG12V-driven lung adenocarcinomas." (PMID 30875794, 2019). "Therefore, our results may provide an explanation of the highly controversial function of SIRT1 in cancer development by linking its expression to its subcellular localization." (PMID 31317367, 2019). "One way to reconcile the opposing effects of SIRT1 on the proliferation of different cells is that certain proliferative tissues including RA-FLS and a subset of cancers may share common SIRT1-dependent signaling pathways distinct from those in other cell types." (PMID 29784872, 2018). "Third, SIRT1 is down-regulated in both RA synovial tissues and RA-FLS as shown by our data, similar to its down-regulation in certain cancers as shown by others, an effect that could be explained by common SIRT1-dependent signaling pathways in these cell types." (PMID 29784872, 2018). "SIRT1 may be oncogenic because its overexpression has been detected in many cancers." (PMID 29636061, 2018). "The downstream signaling pathway of SIRT1 in each cancer might be different." (PMID 29996516, 2018). "Silent information regulator 1 (SIRT1) is a member of Sirtuin family, which is a nicotinamide–adenine dinucleotide-dependent deacylase, with broad regulatory functions in cell apoptosis, differentiation, autophagy, development, cancer metabolism and circadian rhythms." (PMID 30482883, 2018). "Based on these evidences, although still very speculative, the genetic targeting by siRNA or other approaches of Sirt1, Sirt7 or other Sirts in combination with physical exercise might represent an innovative therapeutic approach potentially beneficial in cancer." (PMID 30304806, 2018). "Therefore, SIRT1 may have a preventive or pro-curative pharmacologic application in many disorders in which SIRT1 has a key role, such as cancer, age-related or metabolic disorders." (PMID 29682215, 2018). "Hence, similarly to what has been observed in cancer, Sirt1 might have protective or deleterious effects on the heart depending on the specific pathophysiological environment or in consequence of specific stressor triggers, such as lipids." (PMID 30304806, 2018). "The precise role of SIRT1 in cancer may depend on the specific cell or tumor type." (PMID 29435152, 2018). "In addition, miR‐34a‐mediated Sirt1 has been previously demonstrated to participate in cancer apoptosis, suggesting that miR‐34a‐mediated apoptosis may be one of the reasons that cause hepatocyte apoptosis." (PMID 29873178, 2018). "SIRT1 expression level data could help substantiate human observational evidence for a role of SIRT1 in cancer but expression data are challenging to obtain in large population-based cohorts with long follow-up as expression levels are time-dependent and tissue-specific." (PMID 30410074, 2018). "Furthermore, the NAD(+) – dependent protein deacetylase Sirt1 has been proposed to have a dual role in both control of circadian clock circuitry and promotion of cell survival by inhibiting apoptotic pathways in cancer." (PMID 30210557, 2017). "However, the prognostic value of SIRT1 in these cancers remains inconclusive." (PMID 28977971, 2017). "The further stratified analysis of Asian patients according to cancer type showed a significant association of high SIRT1 expression with worse OS only in non-colorectal gastrointestinal cancer, supporting the results of the subgroup analysis including all patients regardless of geographic location." (PMID 28977971, 2017). "In addition, SIRT1 has been shown to promote survival and inhibit apoptosis of cancer cells." (PMID 28977971, 2017).
cancer (continued). "Regarding SIRT1, which is the only sirtuin studied so far, its overexpression failed to influence the anticancer effects of every‐other‐day fasting (a variation in CR), suggesting that SIRT1 may play a limited role in the effects of CR on cancer." (PMID 28994177, 2017). "SIRT1 may act as either a tumor-suppressor or an onco-protein during cancer development." (PMID 26824501, 2016). "Indeed, several lines of evidence have reported that Sirt1 may have controversial complex roles, either as a cancer suppressor or as a cancer promoter." (PMID 26959057, 2016). "Thus the exact role of SIRT1 in cancer is very controversial." (PMID 26905733, 2016). "However, the role of SIRT1 in cancer has not been clearly understood." (PMID 26992208, 2016). "To date, the antiapoptotic genes OLFM4, SIRT1, PIM-1, and DOCK3, the tumor suppressor PTEN, the cell proliferation and invasion genes CITRON and CLDN10, and FGF9 expressed by cancer-associated fibroblasts have been reported as potential targets for miR-486/miR-486-5p in malignant disease." (PMID 26895105, 2016). "Recent studies demonstrated the recruitment of DNA methyltransferases (DNMTs) enzymes along with SIRT1 to the site of DNA damage as a part of the repair mechanism, which might be defective in cancer cells, resulting in hypermethylation of CpG-island promoters across the double stranded break." (PMID 26459286, 2015). "However, there have been conflicting reports regarding the role of DBC1 and SIRT1 in human cancers." (PMID 25823848, 2015). "In addition to extending lifespan in numerous invertebrates, natural and synthetic SIRT1 activating compounds (STACs) exert beneficial effects on age-related diseases (i.e., cancer, inflammation, cardiovascular diseases, and neurodegeneration), when administered by diet." (PMID 26075037, 2015). "Thus, in cancer cells we may observe increased expression of SIRT1, DNMTs and γ-H2AX proteins, as they are the key markers for genomic stress, DNA damage and repair foci formation." (PMID 26459286, 2015). "Taken together, these results indicate that SIRT1 could act as either a tumour promoter or tumour suppressor, depending on the cellular context or its targets in specific signalling pathways or specific cancers." (PMID 26091232, 2015). "However, in regard to cancer, SIRT1 plays both tumor suppressive and oncogenic roles." (PMID 25907989, 2015). "For cancer therapy, RESV reportedly inhibits cancer progression at the initiation, promotion, and progression steps, and it also has chemoprevention abilities by inhibiting or activating molecular targets such as kinases, cyclooxygenases, ribonucleotide reductase, DNA polymerases, and Sirt1." (PMID 25605016, 2015). "Moreover, little is known about NAMPT and SIRT1 regulation by resveratrol in cancer cells." (PMID 24603648, 2014). "We therefore determined whether SIRT1 inhibition by JQ-101 could inhibit cancer cell invasion." (PMID 25189993, 2014). "We therefore postulated that overexpression of SIRT1 may suppress cancer cell metastasis in vivo." (PMID 25424420, 2014). "Treated mice with resveratrol histone deacetylase sirtuin-1 (HDAC SIRT1) and high-fat diet increase life span, apparently mimicking the well-established contribution of caloric restriction to longevity.Chromatin-modifying agents are currently being tested as novel cancer therapies." (PMID 25045704, 2014). "Excessive SIRT1 activity due to low DBC1 expression might be unfavorable for cancer cell growth." (PMID 25146318, 2014). "This raises the possibility that SIRT1 inhibition might suppress cancer cell proliferation." (PMID 25486244, 2014).
cancer (continued). "Indeed, miR-34a has been shown to be implicated in the dysregulation of cholesterol metabolism by targeting the hepatic NAD-dependent deacetylase Sirtuin 1 (SIRT1), which is critically involved in the modulation of liver cell apoptosis, metabolic disease, and cancer." (PMID 24745023, 2014). "However, there is still a long way to go for treating SIRT1-related diseases such as cancer." (PMID 25486244, 2014). "This decrease of SIRT1 may be corrected by melatonin, as indicated by the few findings obtained in the context of aging, results that contrast, however, with changes observed in melatonin-treated cancer cells." (PMID 25310649, 2014). "In addition, several SIRT1 inhibitors have been tested in cancer xenograft mouse models." (PMID 25189993, 2014). "Consequently, SIRT1 may be regarded as a potential target for the diagnosis and treatment of cancer chemotherapy." (PMID 24137378, 2013). "Therefore, SIRT1 may be identified as a novel target for the selective killing of cancer instead of non-cancer epithelial cells." (PMID 24137378, 2013). "Because SIRT1 has a deacetylase activity against broad range of substrates acting as either tumor promoters or tumor suppressors, activating its enzyme activity may be beneficial for certain subtypes of cancers." (PMID 23846322, 2013). "Thus, SIRT1 inhibition may contribute to the treatment of cancer patients in combination with ROS-producing cancer therapies such as ionizing radiation and alkylating antineoplastic agents." (PMID 24040102, 2013). "Moreover, SIRT1 mediated cellular proliferation was cancer specific." (PMID 24019980, 2013). "Furthermore, both SIRT1 and HDAC3 have been implicated as regulators of several common cellular and physiological functions such as apoptosis, circadian cycle, glucose and lipid metabolism and cancer." (PMID 23841676, 2013). "Preclinical studies suggest that activation of SIRT1 could be a cancer prevention strategy." (PMID 23819063, 2013). "Interestingly, altered NAMPT levels have been implicated in metabolic disorders and cancer, and FK866, a highly specific NAMPT inhibitor that abolishes NAD+ circadian oscillations and thereby SIRT1 cyclic activity, is used to control cell death in human cancer tissues." (PMID 22834651, 2012). "Interestingly, SIRT1 displays differential localization in normal cells and cancer cells, which in turn may affect the substrate specificity for its deacetylase activity." (PMID 23050959, 2012). "As neoplastic cells are thought to recapitulate many stem cell characteristics, the oncogenic function of Sirt1 might also be mediated by aberrant regulation of developmental genes, especially for those cancers in which the undifferentiated phenotype predominates." (PMID 21307403, 2011). "We next examined whether up-regulation of SIRT1 contributed to an N-Myc-induced cancer phenotype." (PMID 21698133, 2011). "Inhibition of Sirt1 by multiple approaches (pharmacologic, over expression of a dominant negative protein or short interfering RNA) leads to TSG re-expression and a block in tumor-causing networks of cell signaling that are activated by loss of the TSGs in a wide range of cancers." (PMID 21549004, 2011). "Although some studies have suggested that SIRT1 may function as a tumor promoter because of its increased expression in some types of cancers, other studies have demonstrated that SIRT1 levels are reduced in some other types of cancers thereby acting as tumor suppressors." (PMID 21980390, 2011).